CRISP3 (cysteine rich secretory protein 3)
Diseases named in the same sentence as CRISP3 in open-access papers (continued):
Sharing a sentence is not in itself a finding about the gene and the disease.
endometriosis (2 papers, 2017 to 2020). The growth of functional endometrial tissue in anatomic sites outside the uterine body. "Nine proteins were quantitatively reduced in endometriosis, including some proteins related with local innate immunity (CRISP-3 and Pglyrp1) and protection against oxidative stress (HSPB1)." (PMID 28174513, 2017). "Nine proteins were reduced in endometriosis, including Azurocidin 1, an important inflammatory mediator, cysteine-rich secretory protein 3 (CRISP-3) and Heat shock protein beta-1 (HSPB1)." (PMID 28174513, 2017). "Repeated genes from the MS-phase (CCN1, CRISP3, EGR1, FOS, FOSB, and TRPM6) could be associated with affected receptivity in endometriosis." (PMID 32474803, 2020). "CRISP-3 is present in exocrine secretions and in secretory granules of neutrophilic granulocytes and is believed to play a role in local innate immunity, which is depressed in patients with endometriosis." (PMID 28174513, 2017).
prostate (2 papers, 2011 to 2012). "CRISP3 has been previously linked to prostate carcinogenesis." (PMID 21814574, 2011).
cervical tumor (1 paper, 2024). "We extended our investigation by assessing CRISP3 expression in representative cervical tumor-derived cell lines." (PMID 39139989, 2024). "In the same population, CRISP3 was isolated and graphically depicted, showing its significant reduction in cervical tumors." (PMID 39139989, 2024). "Through a computational approach, we identified the differential expression of CRISP3, characterized by significantly reduced levels in cervical tumors in comparison with normal tissue." (PMID 39139989, 2024). "Additionally, we provide a transcriptional profile of CRISP3 in different cervical tumor cell lines and its alterations in response to treatment with drugs that regulate epigenetic factors." (PMID 39139989, 2024).
endometritis (1 paper, 2023). An acute or chronic, usually bacterial infectious process affecting the endometrium. "On the other hand, there are also CRISP-3 and lactoferrin in SP with anti-inflammatory effects, which can regulate the secretion of anti-inflammatory cytokines and resist copulation-induced endometritis." (PMID 37834087, 2023). "The role of CRISP-3 in regulating the endometrial environment is also of interest in horses, where it is thought to regulate sperm–neutrophil interactions and to modulate persistent mating-induced endometritis by suppressing the expression of proinflammatory cytokines in the endometrium." (PMID 37834087, 2023).
male infertility (1 paper, 2024). The inability of the male to effect fertilization of an ovum after a specified period of unprotected intercourse. "An aberrant expression of CRISP2 is associated with male infertility due to its participation in gamete fusion; however, to our knowledge, there are no studies on CRISP (CRISP2 and CRISP3) expression in the semen of felid-related species." (PMID 38612267, 2024).
Myalgia (1 paper, 2020). "Cysteine-rich secretory protein 3 (CRISP 3) is another upregulated protein in TMD myalgia patients." (PMID 32272779, 2020).
non-small cell lung carcinoma (1 paper, 2022). A group of at least three distinct histological types of lung cancer, including non-small cell squamous cell carcinoma, adenocarcinoma, and large cell carcinoma. "In non-small cell lung cancer, decreasing CRISP3 expression levels inhibited progression and development of cancer." (PMID 36263172, 2022).
pancreatic cancer (1 paper, 2023). "There is also some evidence that CRISP-3 may be associated with the development of pancreatic cancer lesions in other types of tumours, particularly those which are predominantly found in the gastrointestinal tract." (PMID 37070095, 2023).
prediabetes (1 paper, 2011). "Finally, the Cox regression analysis was performed for glycaemic progression (NGT at baseline -> IGT/IFG/T2DM by CRISPS2 or CRISP3; and IGT/IFG at baseline -> T2DM by CRISP2 or CRISPS3) which involved both incident prediabetes and incident T2DM case subjects." (PMID 22163043, 2011).
rheumatoid arthritis (1 paper, 2022). A chronic, systemic autoimmune disorder characterized by inflammation in the synovial membranes and articular surfaces. "Quantitative proteomics analysis of NETs in response to PMA and A23187 in neutrophils from rheumatoid arthritis and SLE indicated PMA-induced NETs contained proteins of annexin family, azurocidin, and histone H3, whereas A23187 enriched CAMP/LL37, CRISP3, lipocalin, IL-8, and PADI4." (PMID 35622142, 2022).
Sepsis (1 paper, 2024). Sepsis is defined as life-threatening organ dysfunction caused by a dysregulated host response to infection. "Plasma CRISP3 remained significantly associated with a higher risk of sepsis [OR = 1.004 (1.002–1.006), p < 0.001], adjusted by age, sex, and ISS." (PMID 39624089, 2024). "Plasma CRISP3 on admission was significantly associated with the incidence of sepsis [OR = 1.004 (1.002–1.006), p < 0.001]." (PMID 39624089, 2024). "Meanwhile, an AUC [0.772 (0.701–0.834)] of plasma CRISP3 was obtained for the risk of sepsis after trauma." (PMID 39624089, 2024). "In the present research, we utilized publicly available datasets and two cohorts to systematically explore the association between CRISP3 and sepsis." (PMID 39624089, 2024). "This incomplete understanding required us to investigate the underlying mechanisms of how CRISP3 affects the development of sepsis." (PMID 39624089, 2024). "Furthermore, the findings suggested that the concentrations of plasma CRISP3 were significantly associated with the risk of trauma sepsis [OR = 1.003 (1.001–1.005), p = 0.001]." (PMID 39624089, 2024). "Our results found and validated that CRISP3 strongly correlates with the risk of sepsis and that elevated plasma CRISP3 on hospital admission could predict the incidence of sepsis." (PMID 39624089, 2024). "Then, we explored whether plasma CRISP3 could serve as a potential biomarker to predict the risk of sepsis via two retrospective trauma cohorts." (PMID 39624089, 2024). "Further studies are warranted to explore the underlying mechanisms among CRISP3 and sepsis." (PMID 39624089, 2024). "More importantly, CRISP3 may serve as a latent biomarker to predict the risk of sepsis." (PMID 39624089, 2024). "Thus, all of those results suggested that CRISP3 concentrations could serve as a potential biomarker to predict the risk of post-injury sepsis." (PMID 39624089, 2024). "In the current study, we conducted a systematic exploration via public datasets from the ArrayExpress and Gene Expression Omnibus (GEO) databases to determine and verify the clinical significance of CRISP3 in sepsis patients." (PMID 39624089, 2024). "Consistent with the previous findings, sepsis patients had significantly higher plasma CRISP3 compared with non-sepsis patients (1.542 ± 1.075 ng/mL vs. 0.696 ± 0.509 ng/mL, p < 0.001)." (PMID 39624089, 2024). "Generally, our study determined and verified that CRISP3 was significantly elevated in sepsis patients." (PMID 39624089, 2024). "We conducted a comprehensive literature search and meta-analysis from the Gene Expression Omnibus (GEO) and ArrayExpress to determine the expression of CRISP3 in sepsis patients." (PMID 39624089, 2024). "To explore the expression of CRISP3 in sepsis, we performed a comprehensive analysis based on the expression values from the ArrayExpress and GEO databases." (PMID 39624089, 2024). "The results of the meta-analysis suggested that the significant upregulation of CRISP3 in sepsis was observed across all datasets." (PMID 39624089, 2024). "Plasma CRISP3 on admission after injury remained significantly related to the occurrence of sepsis [OR = 1.002 (1.001–1.003), p < 0.001]." (PMID 39624089, 2024). "To further determine the upregulation of CRISP3 concentrations in sepsis, we performed two retrospective studies that included 54 and 166 trauma patients." (PMID 39624089, 2024). "Through analysis of 23 microarray datasets, we observed an increased expression of CRISP3 in sepsis patients." (PMID 39624089, 2024). "A total of 23 datasets were recruited for the comprehensive meta-analysis, and the combined standardized mean difference (SMD) of CRISP3 was 0.90 (0.50–1.30) (p < 0.001), suggesting that CRISP3 was overexpressed in sepsis patients." (PMID 39624089, 2024). "To further indicate the role of plasma CRISP3 in sepsis, we explored the relationships between plasma CRISP3 and SOFA, APACHE II scores, procalcitonin (PCT), and C-reactive protein (CRP)." (PMID 39624089, 2024).
Sepsis (continued). "Nevertheless, no study has explored the relationships between the values of CRISP3 and sepsis." (PMID 39624089, 2024). "Nonetheless, the expression and clinical values of CRISP3 in sepsis were unclear." (PMID 39624089, 2024). "Our study indicated and validated that CRISP3 was highly expressed in sepsis." (PMID 39624089, 2024). "Additionally, we used two retrospective cohorts to verify the correlations between plasma CRISP3 and sepsis following injury." (PMID 39624089, 2024). "Then, we attempt to explore whether plasma CRISP3 could serve as a potential biomarker to predict the occurrence of sepsis via two retrospective cohorts." (PMID 39624089, 2024). "As the most abundant white blood cells, neutrophils are the first line of defense against invading pathogens; thus, we speculated that CRISP3 may affect the spread of pathogens in sepsis by influencing neutrophil activation and degranulation process." (PMID 39624089, 2024). "More importantly, increased CRISP3 may serve as a latent biomarker to predict the incidence of sepsis." (PMID 39624089, 2024). "The results indicated that a random-effects model was performed due to an apparent heterogeneity (p < 0.001, I2 = 90%), and a remarkable overexpression of CRISP3 mRNA was observed in the sepsis patients (n = 2,073) compared with the controls (n = 628) [SMD = 0.85 (0.50–1.20), p < 0.001]." (PMID 39624089, 2024). "Finally, 23 datasets were considered to explore the expression levels of CRISP3 mRNA between controls and sepsis patients." (PMID 39624089, 2024). "Second, we only found plasma CRISP3 was correlated with the incidence of sepsis." (PMID 39624089, 2024). "Additionally, the clinical relationships between plasma CRISP3 and sepsis were verified in another trauma cohort with 166 patients [OR = 1.002 (1.001–1.003), p < 0.001]." (PMID 39624089, 2024). "Thus, we proposed that CRISP3 may contribute to the development of sepsis by affecting the expression or function of ANXA1 or A1BG." (PMID 39624089, 2024). "Therefore, we suggest that CRISP3 may guide clinicians in the early management of sepsis patients to improve outcomes." (PMID 39624089, 2024). "However, the mechanisms of how CRISP3 affects the development of sepsis remain still unclear." (PMID 39624089, 2024). "However, how CRISP3 affects the development of sepsis remains unclear." (PMID 39624089, 2024). "Therefore, we speculated that CRISP3 may participate in the development of sepsis." (PMID 39624089, 2024). "First, our retrospective study indicated and verified that CRISP3 increased in trauma sepsis, but the meta-analysis did not include trauma cohorts." (PMID 39624089, 2024). "Compared with CRP and PCT, CRISP3 had an outperformed ability to discriminate sepsis from non-sepsis individuals." (PMID 39624089, 2024). "Meanwhile, sepsis patients had higher CRISP3 concentrations than non-sepsis patients in 54 trauma patients (p < 0.001)." (PMID 39624089, 2024). "We compared the CRISP3 plasma concentrations between sepsis and non-sepsis patients, and the results revealed that CRISP3 concentrations were greatly elevated in sepsis patients (1.305 ± 0.535 ng/mL vs. 0.743 ± 0.270 ng/mL, p < 0.001), which were in line with the results of the meta-analysis." (PMID 39624089, 2024). "Finally, the meta-analysis suggested that CRISP3 may not influence the prognosis of sepsis patients; thus, we did not explore the relationship between plasma CRISP3 and the outcomes of sepsis patients." (PMID 39624089, 2024).
squamous cell carcinoma (1 paper, 2024). A carcinoma arising from squamous epithelial cells. "CRISP3 levels were significantly lower in patients with squamous cell carcinoma (SCC), compared with adenocarcinoma (P < 0.0001) and other histological subtypes (P = 0.0046)." (PMID 39139989, 2024).
tumor (29 papers, 2011 to 2026). "Inflammatory markers such as S100A8 and CRISP-3 showed differential expression based on lymph node status, reflecting tumor-associated inflammation and potential differences in lymphatic dissemination." (PMID 40710368, 2025). "This may suggest that CRISP3 might be actively released into the bloodstream from the tumor or surrounding tissues which has a potential diagnostic value." (PMID 38918474, 2024). "In breast neoplasms, CRISP3 overexpression is associated with tumor spread and severity." (PMID 39139989, 2024). "This study indicates that DES-associated CRISP3 is associated with poor prognosis in PCa, and it may promote tumor proliferation and metastatic capacity by promoting EMT." (PMID 37070095, 2023). "DES-associated CRISP3 is associated with poor prognosis in PCa, and it may promote tumor proliferation by promoting EMT." (PMID 37070095, 2023). "Cellular experiments revealed that DES-associated CRISP3 is associated with poor prognosis in PCa, and it may promote tumor proliferation and metastatic capacity by promoting EMT." (PMID 37070095, 2023). "Mechanistically, CRISP3 acted as a tumor suppressor through the PI3K/AKT signaling pathway to inhibit the progression and metastasis of HGSOC." (PMID 41751369, 2026). "This dual mechanism highlights the role of CRISP3 in linking hypoxia-driven tumor progression to an adverse immune milieu, ultimately contributing to the poor prognosis observed in high-risk patients." (PMID 41200166, 2025). "The predominantly nodular seeding pattern showed the downregulation of CRISP3 in the tumor region (log2FC = − 1.45, adjusted p-value < 0.001)." (PMID 39135097, 2024). "We observed that tumor samples positive for HPV18 have a significantly higher mean expression of CRISP3 than other viral types (P < 0.05)." (PMID 39139989, 2024). "This study demonstrated that hsa_circ_0003823, as a ceRNA, promoted CRISP3-mediated tumor progression and metastasis in ESCC by inhibiting miR-607." (PMID 36263172, 2022). "The genes with low expression in the tumor group were CRISP3, FAM3D, SCNN1B, CRISP2, RBM20, PHYHIP, C2orf54, SLC5A1, PTCRA, C15orf59, and ANO10." (PMID 35389773, 2022). "Another five genes that were up-regulated with tumor progression showed further increased expressions after chemotherapy (CRISP3, KCNMA1, BDNF, SLC22A4, SYN2)." (PMID 23451142, 2013). "Notably, CRISP3-mediated upregulation of IL-17 in BC cells may contribute to the enrichment of Th17 and γδ T lymphocytes observed in the high-risk group, suggesting a potential feed-forward loop between tumor-intrinsic signaling and immune microenvironment remodeling." (PMID 41200166, 2025). "Additionally, we conducted an analysis using the GENT2 platform and observed that, in other populations, the expression of CRISP3 is also significantly reduced in tumor samples." (PMID 39139989, 2024). "Spatial domains 6 and 8, forming the fibrotic region of invasive cancer, had the highest number of SVGs (223 and 242, respectively), with significant expression of CRISP3, a protein potentially influencing the tumor microenvironment and promoting cancer invasion." (PMID 39701602, 2024). "Regarding treatment, TSA was able to increase CRISP3 transcription in all analyzed tumor cell lines, suggesting that epigenetic regulation based on histone activity may be present." (PMID 39139989, 2024). "Interestingly, upregulated DEGs like SNCG (logFC 9.95), CPNE8 (logFC 7.18), GRIA3 (logFC 4.08), SOX5 (logFC 3.94) and CRISP3 (logFC 3.44) representing the highest log fold changes were involved in tumor cell metastasis and invasiveness." (PMID 37239828, 2023). "Further functional and mechanistic studies have shown that hsa_circ_0003823 could act as a sponge for miR-607, alleviating its inhibition on the target gene CRISP3, thereby promoting tumor progression, metastasis and Apatinib resistance." (PMID 36263172, 2022).